TAPT1 (transmembrane anterior posterior transformation 1)
Description:
Plays a role in primary cilia formation. May act as a downstream effector of HOXC8 possibly by transducing or transmitting extracellular information required for axial skeletal patterning during development (By similarity). May be involved in cartilage and bone development (By similarity). May play a role in the differentiation of cranial neural crest cells (By similarity). (Microbial infection) In case of infection, may act as a fusion receptor for cytomegalovirus (HCMV) strain AD169.
Synonyms: CMVFR; FLJ90013; OCLSBG
Tractability: Antibody: UniProt predicts a signal peptide or a membrane-spanning region. PROTAC: ubiquitination databases record sites on it; its protein half-life has been measured.
Gene: Protein-coding gene on chromosome 4 (16,160,505 to 16,227,410, reverse strand). Ensembl gene ENSG00000169762.
Subcellular location: Cytoplasm, cytoskeleton, microtubule organizing center, centrosome; Cytoplasm, cytoskeleton, cilium basal body; Membrane
Subcellular location (Human Protein Atlas): Basal body; Centrosome; Cytosol; Nucleoplasm
Gene Ontology:
Molecular function: growth hormone-releasing hormone receptor activity
Biological process: positive regulation of cilium assembly; neural crest cell development; positive regulation of bone development; positive regulation of cartilage development; G protein-coupled receptor signaling pathway
Cellular component: centrosome; ciliary basal body; endoplasmic reticulum membrane; membrane
Genetic constraint (gnomAD): Loss-of-function variants: 13 observed, 29.61 expected, observed/expected ratio (o/e) 0.44, 90% interval 0.28 to 0.7. The synonymous counts are far from expectation, so gnomAD's model fits this gene poorly and the ratio says little. Missense variants: 424 observed, 441.4 expected, observed/expected ratio (o/e) 0.96, 90% interval 0.89 to 1.04. Synonymous variants: 211 observed, 166.21 expected, observed/expected ratio (o/e) 1.27, 90% interval 1.13 to 1.42.
Homologues: Orthologues: chimpanzee TAPT1 (99% identical), macaque TAPT1 (99% identical), mouse Tapt1 (95% identical), rat Tapt1 (95% identical), pig TAPT1 (94% identical), dog TAPT1 (93% identical), guinea pig TAPT1 (88% identical), rabbit TAPT1 (80% identical), tropical clawed frog tapt1 (78% identical), zebrafish tapt1b (77% identical), zebrafish tapt1a (70% identical), Drosophila melanogaster CG7218 (41% identical), and 1 more.
Diseases named in the same sentence as TAPT1 in open-access papers:
TAPT1 is named in the same sentence as 23 diseases in open-access papers, as found by Europe PMC text mining. Sharing a sentence is not in itself a finding about the gene and the disease. The quoted sentences say what the papers report.
leukemia (3 papers, 2020 to 2024). A malignant (clonal) hematologic disorder, involving hematopoietic stem cells and characterized by the presence of primitive or atypical myeloid or lymphoid cells in the bone marrow and the blood. "TAPT1 expression is suppressed by polycomb repressive complex 2 (PRC2) in leukemia cells, although the functional significance of TAPT1 suppression was not determined." (PMID 33374314, 2020). "PROM1 promoter repression by polycomb repressive complex 2 (PCR2) in CD133-negative leukemia cells impair the interaction between the PROM1 promoter and the intragenic PROM1 and TAPT1 enhancers, explaining the absence of CD133 expression." (PMID 37922108, 2024).
breast carcinoma (2 papers, 2020 to 2022). "Importantly, reduced TAPT1 expression correlated with an increased risk of relapse in breast cancer patients." (PMID 33374314, 2020). "Indeed, higher TAPT1 expression correlated with an improved chance of disease-free survival in a pan-analysis of breast cancer patients." (PMID 33374314, 2020). "Notably, further inquiry into TAPT1 regulation and function is supported by the correlation between reduced TAPT1 expression and worse patient outcomes in breast cancer and NSCLC patients." (PMID 33374314, 2020). "Moreover, reduced TAPT1 expression correlated with worse odds of relapse-free survival in breast cancer and non-small cell lung cancer (NSCLC) patients." (PMID 33374314, 2020). "Together, our results reveal how increased miR614 expression and the suppression of TAPT1 and Miro1 modulate the EMT state and migratory properties of breast cancer cells." (PMID 33374314, 2020).
hepatocellular carcinoma (2 papers, 2020 to 2022). A malignant tumor that arises from hepatocytes. "In terms of the contribution of APA to TAPT1 in different tumor types, APA modification affects the 3′UTR of TAPT1 in hepatocellular carcinoma cell lines, indicating that this specific pattern of APA modification may contribute to the identification of LIHC from other tumor types." (PMID 32626751, 2020).
osteochondrodysplasia (2 papers, 2022 to 2023). A term referring to disorders characterized by abnormalities in the development of bones and cartilage. "Our results also suggested that two lethal osteochondrodysplasia-associated mutations of TAPT1 likely function as gain-of-function (GOF) variants to promote SMAD1 proteasomal degradation." (PMID 36370851, 2022). "Although loss‐of‐function mutations in TAPT1, SUCO and P4HB in humans all result in osteochondrodysplasia‐like phenotypes, the homologs of these genes in lower organisms lead to unrelated phenotypes when absent." (PMID 36652330, 2023). "Two homozygous TAPT1 mutations, TAPT1D353V and TAPT1Δexon10, cause a congenital syndrome with complex lethal osteochondrodysplasia, showing severe hypomineralization of the entire skeleton." (PMID 36370851, 2022). "Genetic defects in TAPT1 result in complex lethal osteochondrodysplasia." (PMID 36370851, 2022).
ciliopathy (1 paper, 2024). A genetic disorder of the cellular cilia or the cilia anchoring structures, the basal bodies, or of ciliary function. "The studies show the involvement of TAPT1 in the basis of a complex congenital syndrome clinically manifested by lethal skeletal dysplasias and ciliopathy." (PMID 38271973, 2024).
collagenopathy (1 paper, 2023). "The clinical manifestations and transcriptomics results shown here support the hypothesis that TAPT1‐deficiency belongs to the heterogeneous group of collagenopathies." (PMID 36652330, 2023).
HCMV infection (1 paper, 2023). "TAPT1 which codes for a predicted transmembrane protein is involved in ER/Golgi pathways, human Cytomegalovirus (HCMV) infection and primary ciliogenesis." (PMID 36652330, 2023). "Our β‐gal reporter assay showed no discernable differences between WT and mutant patient cells, hence indicating that TAPT1 is not essential for HCMV infection, further suggesting the likely presence of other cellular receptors which would permit HCMV cellular entry in the absence of TAPT1." (PMID 36652330, 2023).
lipodystrophy (1 paper, 2023). A congenital or acquired disorder characterized by abnormal loss or redistribution of the adipose tissue in the body. "In addition to the shared clinical features with these previously reported TAPT1‐deficient patients, including bone abnormalities and cataract, our affected children also suffered from neonatal progeria, characterized by wrinkled and thin skin, premature depigmentation and lipodystrophy." (PMID 36652330, 2023).
malaria (1 paper, 2023). Malaria is a serious and sometimes fatal disease caused by a parasite that commonly infects a certain type of mosquito which feeds on humans. "In Plasmodium falciparum, the causative pathogen for malaria, mutations in TAPT1's homolog, pfcarl, confer resistance to various structurally unrelated antimalarial compounds which appear to target the ER/Golgi function of the parasite." (PMID 36652330, 2023).
Obesity (1 paper, 2019). Accumulation of substantial excess body fat. "Several of these cis-eQTLs influence the mRNA levels of genes with important roles in meat (CTSF) and carcass quality (TAPT1), lipid metabolism (TMEM97) and obesity (MARC2), thus evidencing the practical importance of dissecting the genetic mechanisms involved in their expression." (PMID 31234802, 2019).
skeletal dysplasia (3 papers, 2022 to 2024). Any Mendelian diseases that affects growth and development of the skeleton. "These enhanced effects of TAPT1 mutations on BMP signaling are likely to cause the clinical phenotype of skeletal dysplasias." (PMID 36370851, 2022). "In addition, genetic mutations in TAPT1 cause complex lethal skeletal dysplasias and ciliopathies with severe hypomineralization of the entire skeleton as well as intrauterine fractures." (PMID 36370851, 2022). "Importantly, a subset of TAPT1 mutations identified in humans with lethal skeletal dysplasia exhibited gain-of-function activity on SMAD1 protein levels." (PMID 36370851, 2022). "In humans, TAPT1 mutations show a clinical phenotype with lethal skeletal dysplasia." (PMID 36370851, 2022). "Notably, mutations in SUCO and P4HB have been linked to skeletal dysplasia in humans, which aligns with the TAPT1 loss‐of‐function clinical presentation." (PMID 36652330, 2023).
cancer (2 papers, 2016 to 2017). A tumor composed of atypical neoplastic, often pleomorphic cells that invade other tissues. "Likewise, we found a number of genes whose expression follows this pattern: late-stage cancers < early-stage cancers < normal tissue, such as ADHFE1, LOC653501, NT5DC1, RSBN1, SOCS2 and TAPT1 in five cancer types." (PMID 28427185, 2017).
tumor (2 papers, 2020). "Given the ubiquitous expression of TAPT1, it may act as suppressor of migration and serve as a biomarker for patient outcome in additional tumor types." (PMID 33374314, 2020). "By contrast, other genes, including COPS7A, TAPT1, PAPD4, C4orf3, and HMGB2, have a tumor suppressor effect, and their high expression levels characterize patients with a good survival potential." (PMID 32626751, 2020). "Notably, a correlation between high TAPT1 expression and improved odds of survival was also detected when analyzing non-small cell lung cancer (NSCLC) patients, suggesting that TAPT1 may generally influence tumor progression." (PMID 33374314, 2020).
infection (1 paper, 2023). The state of being infected such as from the introduction of a foreign agent such as serum, vaccine, antigenic substance or organism. "We revisited this claim by testing whether human TAPT1‐null patient cells were resistant to HCMV strain RC256 infection." (PMID 36652330, 2023).
TAPT1 also shares sentences with these, for which no sentence is quoted: chondrodysplasia (1 paper); lung carcinoma (1); lung disease (1); lupus (1); lymphoma (1); melanoma (1); non-small cell lung carcinoma (1); pancreatic cancer (1); progeroid syndrome (1).